TMSB4XP8 (TMSB4X pseudogene 8)
Synonyms: formerly TMSL3
Gene: Processed pseudogene on chromosome 4 (90,838,903 to 90,839,037, reverse strand). Ensembl gene ENSG00000187653.
Diseases named in the same sentence as TMSB4XP8 in open-access papers:
TMSB4XP8 is named in the same sentence as 1 disease in open-access papers, as found by Europe PMC text mining. Sharing a sentence is not in itself a finding about the gene and the disease. The quoted sentences say what the papers report.
cancer (3 papers, 2013 to 2024). A tumor composed of atypical neoplastic, often pleomorphic cells that invade other tissues. "Importantly, our investigation revealed a novel cancer disease indicator, TMSB4XP8, potentially stemming from off‐target overexpression." (PMID 38887841, 2024). "A deeper examination of the feature importance of the cancer detection model has revealed the top five transcripts at play: FKBP5, TMSB4XP8, MTRNR2L12, HBB, and SPDYC." (PMID 38887841, 2024). "The exploration of the feature importance of the cancer detection model has pinpointed the top five transcripts characterized by their largest weight on prediction outcomes: FKBP5, TMSB4XP8, MTRNR2L12, HBB, and SPDYC." (PMID 38887841, 2024).